TRPV4 (transient receptor potential cation channel subfamily V member 4)
Diseases named in the same sentence as TRPV4 in open-access papers (continued):
Sharing a sentence is not in itself a finding about the gene and the disease.
ischemia (continued). "This is the first study that describes the impact of AQP4/TRPV4 deletion on the size of the ischemic lesion (MRI) and ECS diffusion parameters in experimental models of ischemia, OGD, hyperkalemia, and hypotonic stress in AQP4–/–/TRPV4–/– mice." (PMID 36568889, 2022). "We used three models of ischemia-related pathological conditions: hypoosmotic stress, hyperkalemia, and oxygenglucose deprivation (OGD), and observed their effect on astrocyte volume changes in acute brain slices of Aqp4–/–, Trpv4–/– and double knockouts." (PMID 38818517, 2024). "Little inducibility was found in all groups at baseline, but the number of total ventricular tachyarrhythmias (VTA) after regional ischemia were significantly higher in TRPV4+/+ animals of the HF(iso) group compared to TRPV4+/+ sham and TRPV4−/− receiving isoproterenol." (PMID 38338818, 2024). "Transient receptor potential vanilloid 4 (TRPV4) is a Ca2+-permeable nonselective cation channel and can be activated during ischemia/reperfusion (I/R)." (PMID 28205608, 2017). "In the present study we showed that not all hippocampal astrocytes responded to TRPV4-agonist in control rats, but the number of responding cells significantly increased after ischemia." (PMID 22761937, 2012). "Astrocytic Transient receptor potential vanilloid 4 (TRPV4) channels, together with Aquaporin 4 (AQP4), are suspected to be the key players in cellular volume regulation, and therefore may affect the development and severity of cerebral edema during ischemia." (PMID 38818517, 2024). "Since ischemia is accompanied by a profound increase in [K+]o, we also estimated extracellular K+ concentrations evoked by OGD, with the expectation that they may differ in the Ctrl and AQP4–/–/TRPV4–/– mice." (PMID 36568889, 2022). "Furthermore, increased TRPV4 expression and function have been found in the rat hippocampal CA1 region of the brain, which in response to exposure to hypoxia and ischemia episodes was found to result in development of astrogliosis and predicted to influence and/or disrupt neurovascular coupling." (PMID 28472069, 2017). "However, there are no data demonstrating the functional expression of TRPV4 channels in astrocytes in situ under either physiological or pathophysiological conditions, such as ischemia." (PMID 22761937, 2012).
glaucoma (23 papers, 2016 to 2025). Increased pressure in the eyeball due to obstruction of the outflow of aqueous humor. "Mechanosensitive ion channels, such as transient receptor potential cation channel subfamily V member 4 (TRPV4) and Piezo1, are postulated to be implicated in the development of glaucoma." (PMID 39337712, 2024). "We found that TRPV4 played an essential role in glaucoma, such that high levels of TRPV4 expression were associated with elevated intraocular pressure." (PMID 34789280, 2021). "Previous studies in search of finding new treatments for glaucoma have shown that TRPV4 is linked to trabecular meshwork cells." (PMID 28368307, 2017). "Because TRPV4 tends to be localized to cell types that are susceptible to glaucoma (RGCs, Müller glia, microglia, endothelial cells), its targeting may achieve the quadfecta of IOP lowering, reduced neuroinflammation, reduced ischemia, and neuroprotection." (PMID 39041037, 2024). "The functional impairment of TRPV4-eNOS signaling in glaucoma rendering TM cells insensitive to fluid flow–induced shear stress and result in the pathological elevation of IOP." (PMID 41561623, 2025). "Further, dysregulation of transient receptor potential cation channel subfamily V member 4 (TRPV4), a calcium channel, has been implicated in glaucoma." (PMID 40650044, 2025). "Our central finding is that the glaucoma-inducing cytokine TGFβ2 amplifies TRPV4 expression and activity, which in turn drives tonic increases in TRPV4 activation and TM contractility that are required to maintain elevated IOP." (PMID 39574569, 2025). "As such, TRPV4 perpetuates the vicious feedback loop between mechanical stressors and TM contractility and thus represents an ideal therapeutic target in glaucoma cases that resist current treatments." (PMID 39574569, 2025). "The higher level of depolarizing TRPV4 in RGCs is consistent with their higher pressure-vulnerability observed in glaucoma and traumatic retinal injury compared to other neurons." (PMID 39606631, 2024). "The channel opening was associated with RGC apoptosis, and TRPV4 antagonists have showed neuroprotective effects on RGC survival in vitro and in a rat glaucoma model." (PMID 39606631, 2024). "In fact, TRPV4 has been considered a potential therapeutic target to treat glaucoma because its inhibition has been found to improve the survival of RGCs Taken together, these studies highlight TRPV4 as a potential target in treating glaucoma." (PMID 35185615, 2022). "In glaucoma, it was suggested that impaired mechanosensing of TRPV4 in trabecular meshwork cells with compromised primary cilia contributes to increased intraocular pressure." (PMID 35323756, 2022). "In the eyeball, the transient receptor potential vanilloid receptor 4 (TRPV4) has been studied extensively in the TRP family concerning glaucoma." (PMID 35185615, 2022). "TRPV4 sparklet activity per site and the number of sparklet sites per cell were significantly lower in TM cells from glaucoma patients." (PMID 33853948, 2021). "Our study findings complement the changes in TRPV4 expression in the context of ocular hypertension; they also suggest that TRPV4 can serve as a therapeutic target in glaucoma." (PMID 34789280, 2021). "Western blot analysis demonstrated slightly increased TRPV4 protein levels in glaucomatous TM cells, indicating that impaired channel regulation, rather than channel expression, contributes to the lowering of TRPV4 channel activity in glaucoma." (PMID 33853948, 2021). "In this sense, the release of Ap4A is produced by the activation of a pressure sensor, a TRPV4 channel, which is activated by the abnormal IOP often associated to glaucoma." (PMID 29085298, 2017). "The dramatic IOP lowering induced by topical or systemic application of TRPV4 blockers in our animal glaucoma model was achieved by breaking the link between TRPV4 activation and activation of downstream calcium-dependent signaling pathways." (PMID 27510430, 2016).
glaucoma (continued). "Taken together, although the specific mechanisms of Piezo1-mediated glaucoma pathogenesis and TRPV4-eNOS pathway remain unclear at the molecular level, it suggests potential for novel therapeutic target for glaucoma." (PMID 41561623, 2025). "The role of TRPV4 extends to glaucoma pathology, particularly in the TM." (PMID 39940776, 2025). "Targeting TRPV4 channel expression and function within the anterior eye might therefore serve as a neuroprotective strategy in glaucoma." (PMID 39041037, 2024). "The TRPV4-dependence of the remarkable facility increases in glucocorticoid-treated cells implicates the channel in outflow suppression in steroid glaucoma." (PMID 39041037, 2024). "Therefore, this study provides evidence that TRPV4 is closely related to glaucoma pathophysiology through Müller gliosis and TNF-α production." (PMID 35563594, 2022). "Because TRPV4 activation in Müller cells reflects glaucoma pathophysiology, statins may have the potential to prevent RGC death." (PMID 35563594, 2022). "The substantial calcium ion influx induced by TRPV4 activation may also trigger multiple calcium cascades that affect RGC apoptosis in glaucoma; further studies are needed to determine how TRPV4 expression by RGCs directly affects RGC apoptosis." (PMID 34789280, 2021). "Furthermore, TRPV4 activation can lead to apoptosis in photoreceptor cells and RGCs, indicating that TRPV4 is involved in retinal detachment and glaucoma." (PMID 34789280, 2021). "In the central nervous system, TRPV4 activation may enhance inflammation and induce cytotoxicity, but it remains unknown whether these effects are involved in glaucoma-related RGC damage." (PMID 34789280, 2021). "We presumed that the mechanosensitive TRPV4 and Piezo channels in the retina could be activated during the onset of glaucoma, thereby triggering multiple subsequent interactions that involve Ca2+ influx." (PMID 34789280, 2021). "TRPV4 activation induces Müller cell gliosis and TNF-α elevation via the JAK2/STAT3/NF-κB pathway, which may exacerbate RGC apoptosis in glaucoma; these results suggest that TRPV4 can serve as a therapeutic target in glaucoma treatment." (PMID 34789280, 2021). "TRPV4 activation in trabecular meshwork by agonists such as GSK1016790A could be a novel treatment for glaucoma." (PMID 34673834, 2021). "Furthermore, TRPV4 activation was involved in glaucoma-induced RGC apoptosis and RGC-related reductions in visual function." (PMID 34789280, 2021). "TRPV4 is widely distributed in the retina and its sustained activation leads to RGC death; indicating that TRPV4 may be a possible target for glaucoma treatment." (PMID 34789280, 2021). "The results, in line with others’ findings, suggest that TRPV4 and BCs may play some roles in glaucoma." (PMID 31064977, 2019). "Targeting TRPV4 may have therapeutic benefits that lead to lowering IOP in glaucoma patients." (PMID 34673834, 2021). "Considering that current glaucoma treatments target secondary outflow mechanisms or incur side effects (such as hyperemia), the IOP lowering achieved through TRPV4 inhibition and gene knockdown promises a novel therapeutic avenue to mitigate ocular injury." (PMID 39574569, 2025). "This study shows that TRPV4 channels are required for induction of OHT by the circadian cycle and pathological interventions that mimic primary and secondary glaucoma." (PMID 39041037, 2024). "Our results also provide evidence that impaired TRPV4 channel activity in TM cells contributes to TM dysfunction and elevated IOP in glaucoma." (PMID 33853948, 2021). "The TRPV4-dependence of OHT under conditions that mimic primary and secondary glaucomas could be explored as a novel target for glaucoma treatments." (PMID 39041037, 2024). "While myopia has not been previously reported in individuals with TRPV4-related disorders, its potential role in the development of eye diseases such as glaucoma and retinopathy has already been described." (PMID 39495751, 2024).
glaucoma (continued). "Although some studies have shown that increased IOP activates TRPV4, it is not well-established that TRPV4 activation in Müller cells is linked with TNF-α production and glaucoma pathology." (PMID 35563594, 2022). "Importantly, we show that impaired TRPV4 channel activity results in reduced NO bioavailability and elevated IOP in glaucoma." (PMID 33853948, 2021). "TRPV4 activation mediates Ca2+ influx in the trabecular meshwork which, after the use of an antagonist for this channel, resulted in a decrease in IOP in a murine model of glaucoma." (PMID 28368307, 2017). "Our results show that TM TRPV4 represents a crucial link between membrane stretch, Ca2+ signals and cytoskeletal reorganization, and that TRPV4 activation is required for persistent IOP elevation in an animal model of glaucoma." (PMID 27510430, 2016). "In this study, we present evidence that TRPV4 is critically involved in the transduction of mechanical stress in TM cells and link overactivation of this force-sensitive channel to maintaining elevated IOP in a mouse model of glaucoma." (PMID 27510430, 2016). "We found that TNF-α production was increased by TRPV4 activation in MIO-M1 cells and decreased by statins, implying that statins could be therapeutic agents with neuroprotective effects for glaucoma patients, if proven by animal models, which will be our next research project." (PMID 35563594, 2022). "Therefore, TRPV4 has potential as a therapeutic target for IOP control and glaucoma." (PMID 34673834, 2021). "However, TRPV4 expression and the specific mechanisms underlying TRPV4-mediated RGC injury in glaucoma have not been fully elucidated." (PMID 34789280, 2021). "In addition, TRPV4 activation could directly lead to the release of inflammatory factors, particularly TNF-α, which participates in RGC apoptosis in glaucoma." (PMID 34789280, 2021). "Considering that TRPV4 can mediate RGC apoptosis through diverse mechanisms that involve Müller cells and RGCs, it may serve as a therapeutic target for preventing RGC apoptosis in glaucoma." (PMID 34789280, 2021). "Finally, TRPV4 inhibition led to reduced Müller cell reactivity, as well as lower overall levels of GFAP expression, TNF-α release, and RGC apoptosis; these findings implied that TRPV4 activation-mediated inflammatory factors were involved in RGC apoptosis in glaucoma." (PMID 34789280, 2021). "In addition, TRPV4 activation could enhance the release of inflammatory cytokines (e.g., tumor necrosis factor-α [TNF-α]) through JAK2/STAT3/NF-kB signaling pathways in Müller cells and elevated expression of TNF receptor 1 in RGCs; this process is involved in RGC apoptosis during glaucoma." (PMID 34789280, 2021).
glioma (23 papers, 2020 to 2026). A benign or malignant brain and spinal cord tumor that arises from glial cells (astrocytes, oligodendrocytes, ependymal cells). "A previous study has found that lethal mitophagy causes cannabidiol’s antitumor effect in glioma and identified that transient receptor potential cation channel subfamily V member 4 (TRPV4) is a target for mitophagy initiation." (PMID 34204169, 2021). "High TRPV4 levels were linked to more aggressive tumorsand poorer survival in patients with glioma." (PMID 41288593, 2026). "Accordingly, TRPV4 overexpression is associated with poor prognosis in glioma patients." (PMID 36158191, 2022). "Previous studies have revealed that the active TRPV4 channel induced autophagy in rat hepatic stellate cells, human glioma cells, and osteoclastic cells." (PMID 41341920, 2025). "Pharmacologically inhibiting TRPV4 with HC067047 or reducing the presence of TRPV4 has been found to effectively prevent metastasis, as demonstrated in glioma cells." (PMID 39337406, 2024). "Among the TRP channels, TRPV4 (transient receptor potential vanilloid 4) expression is considerably higher in malignant glioma compared to both normal brain tissue and low-grade glioma." (PMID 37895420, 2023). "Notably, a team of researchers investigated the impact of cannabidiol (CBD) on glioma and showed that TRPV4-mediated calcium influx triggered mitophagy, leading to the hypothesis that this might be the primary cause of glioma cell death in response to CBD treatment." (PMID 37895420, 2023). "Nonetheless, it has been shown that TRPV4 promotes glioma cell migration and invasion through Akt signalling and regulating the formation of cellular protrusions." (PMID 36497413, 2022). "TRPV4 is upregulated in glioma, positively correlates with tumour grade in glioma patients, and is associated with a worse prognosis." (PMID 36497413, 2022). "Consistent with this, cannabidiol-induced death of glioma cells is mediated via TRPV4-driven mitophagy." (PMID 36619170, 2022). "TRPV4 also accelerates glioma cell migration and invasion through Akt phosphorylation and Rac1 activation." (PMID 36158191, 2022). "In particular, the tumorigenic potential of TRPV4 comes from its critical involvement in glioma cell migration and invasion." (PMID 33928077, 2021). "Accordingly, TRPV4 blockade, induced by the specific TRPV4 inhibitor HC-067047, was found to decrease motility and invasiveness of U87 glioma cells through a P-AKT and Rac1 signaling pathway." (PMID 33928077, 2021). "Their findings suggest a novel TRPV4-CBD-mitophagy pathway in glioma and combination of CBD and TMZ as a potential to explore in future clinical studies." (PMID 34259916, 2021). "More specifically, TRPV1 and TRPV2 have revealed a protective role in glioma cells by regulating cell proliferation and survival, stem cell differentiation and sensitivity to drugs, whereas TRPV4 was found to increase cancer cell invasiveness." (PMID 33928077, 2021). "Here, we discuss the potential as biological markers of diagnosis and prognosis of TRPC6, TRPM8, TRPV4, or TRPV1/V2 being associated with glioma patient overall survival." (PMID 33928077, 2021). "It was also reported that TRPV4 regulates migration and invasion of glioma cells via Rac1 signaling." (PMID 33262217, 2021). "Next, to test the possibility of TRPV4 as a prognostic marker for glioma patients, we analyzed the TRPV4 mRNA levels in the TCGA-glioma dataset." (PMID 32843668, 2020). "Our study demonstrated that TRPV4 mediated glioma cell migration and invasion, which strengthens the idea that TRPV4 is essential for tumor invasiveness." (PMID 32843668, 2020). "Here, we reported that TRPV4 expression was significantly elevated in malignant glioma compared to normal brain and low-grade glioma, and TRPV4 expression was negatively correlated with the prognosis of glioma patients." (PMID 32843668, 2020).